GSK3B (glycogen synthase kinase 3 beta)
Diseases named in the same sentence as GSK3B in open-access papers (continued):
Sharing a sentence is not in itself a finding about the gene and the disease.
depression (continued). "In addition, as expected, several targets (NR3C1, GSK3B, EGM_09788) with high scores were related to depression and age-related decline." (PMID 25105297, 2014). "Interestingly, a number of patents regarding GSK-3β inhibition as the therapeutic mechanism for treatment of neuropsychiatric disorders are being launched, including treatment of depression." (PMID 23862076, 2013). "The presence of GSK3B as the central node of this cluster strengthen its involvement in mood regulation, antidepressant response, and inflammatory hypothesis of depression." (PMID 41550142, 2026). "Moreover, both depression and AD have connections with GSK3β and DVL3." (PMID 37501340, 2024). "Thus, GSK3β is critical to both AD and depression development." (PMID 37501340, 2024). "Therefore, it appears that on one side, there are antioxidant systems and growth factors promoting plasticity, such as Nrf2–HO-1, BDNF, Akt, TrkB, and CREB, which are protective from depression and, on the other side, GSK-3β and NF-κB, which promote depressive behaviour." (PMID 37107192, 2023). "Therefore, it seems that modulation at the level of Gsk-3β may be a potential point of drug action in treatment-resistant depression." (PMID 36983013, 2023). "Additionally, animal models of stress-induced depression have shown increased GSK-3β activity." (PMID 37629191, 2023). "Therefore, the outcome of increased phospho-GSK3β with lithium for improving depression, mania, or both remains unclear." (PMID 36676744, 2023). "HFD may induce depression in rats by desensitizing the Akt/GSK3β signaling pathway to 5-HT in the DG subgranular region of the hippocampal dentate gyrus, and returning to a normal diet can rescue the Akt/GSK3β response to 5-HT and alleviate depression-like behaviors." (PMID 37108261, 2023). "The negative consequences of depression risk factors could thus be counteracted by procedures that lead to GSK3β inhibition." (PMID 36979785, 2023). "Thus, EGCG may alleviate anxiety and depression-like behaviors in mice by downregulating Sema3A and increasing GSK3β phosphorylation in the hippocampus, and has potential application in the treatment of PPD." (PMID 36776771, 2022). "This may be because gestational stress affects the function but not the expression of CRMP2 or because another downstream effector of GSK3β mediates the anxiety and depression-like symptoms observed in PPD; additional studies are needed to investigate these possibilities." (PMID 36776771, 2022). "Besides evidence of GSK3β important regulatory effects in neuronal survival, increasing reports suggest its involvement in the pathophysiological mechanisms of depression, as GSK3β inhibitors have anti-depressant effects and ameliorate depressive-like behavior in animal models." (PMID 34721013, 2021). "As an inhibitor of 5-LO, emodin prevented the depression behaviors along with a series of pathological changes in the hippocampus, such as hippocampal neuron and spine loss, microglial activation, increased IL-1β and TNF-α, and the activation of 5-LO and GSK3β." (PMID 34381778, 2021). "Whether increasing GSK3β can reverse addiction and depression phenotypes still needs to be tested." (PMID 32694984, 2020). "GMDR was used to analyze the interaction between the GSK3β rs6438552, rs334558, and rs2199503 gene polymorphisms with negative life events and depression, and the results showed that there are interactions between GSK-3β rs6438552, rs334558, and rs2199503 polymorphisms and negative life events." (PMID 33658947, 2020). "Recent investigations reported that prevention of GSK-3β might ameliorate depression." (PMID 33292508, 2020). "Despite a variety of hypotheses considering potential factors and risks in the pathogenesis of MDD, nearly all of the hypotheses can be considered in the context of the GSK3β activity, which places the kinase at a central point of depression development and treatment." (PMID 32188010, 2020).
depression (continued). "Interestingly though, and consistent with our data, GSK3B gene expression but not protein levels, was reduced in the nucleus accumbens of depression-susceptible animals in a chronic social defeat model of depression." (PMID 23075086, 2012). "Administration of Schisandrae chinensis fructus showed a promising therapeutic effect on depression induced by CUMS though activation of BDNF and upregulation of TrkB/CREB/ERK and PI3K/AKT/GSK3β/mTOR signaling pathways." (PMID 40612748, 2025). "GSK3β polymorphisms have also been linked to reduced GM (grey matter) volume in the hippocampus and superior temporal gyrus (STG), yet it remains unclear whether these structural differences precede or result from major depressive disorder (MDD), necessitating further research." (PMID 40770700, 2025). "In contrast, another study conducted with elderly patients with depression revealed significantly lower p‐GSK‐3β levels and lower GSK‐3β ratio, suggesting increased GSK3B activity." (PMID 40757845, 2025). "All these findings suggest that upregulation of SIRT1 inhibits the levels of inflammatory factors such as GSK3β, TNF-α, and NF-κB to suppress the inflammatory response and exhibit anti-inflammatory effects, thereby improving depression-like behaviors." (PMID 37239191, 2023). "This review summarizes the pharmacological regulations of natural products from TCM in the prevention and treatment of depression from the aspects of transcription factors (CREB, NF-κB, Nrf2) and molecular signaling pathways (BDNF-TrkB, MAPK, GSK-3β, TLR-4)." (PMID 35923544, 2022). "The target-pathway network illustrated that AKT1, MAPK1, GSK3B, TNF, MTOR, and PTEN were core targets enriched in key signaling pathways that played crucial roles in the treatment of depression by CCHP." (PMID 34976096, 2021). "Thus, GSK3β may play more important roles in depression than GSK3α." (PMID 34051074, 2021). "Single nucleotide polymorphism (SNP) rs6782799 in GSK3β gene has been demonstrated to be important for susceptibility to MDD by modification of the relationship between negative life events and depression." (PMID 32188010, 2020). "In brief, increased GSK3β mRNA expression was found in post-mortem hippocampal samples from MDD patients, which is consistent with previous animal studies of depression." (PMID 30310078, 2018). "Inhibitory actions at nAChR (nicotinic cholinergic receptor), GSK3β (glycogen synthase kinase 3beta) and NOS (nitric oxide synthase) are also pertinent to mechanisms of depression." (PMID 28713269, 2017). "Previous studies have shown that hippocampal GSK-3β activity significantly increased in CMS-treated rats or patients with major depressive disorders, and antidepressant behavior was observed in CMS rats treated with GSK-3β inhibitors." (PMID 24523822, 2014). "In summary, miR-542-3p downregulates PTEN to activate the AKT/GSK3β/β-catenin pathway, thereby reducing apoptosis, repairing hippocampal neuronal damage, restoring neural structure and function, and alleviating CORT-induced depression in mice." (PMID 40043208, 2025). "In addition, baicalin can inhibit the activation of the glycogen synthase kinase-3 beta (GSK3β)/NF-κB/NLRP3 pathway, promoting neuronal maturation and protecting against neuronal damage, thereby alleviating CUMS-induced depression-like behavior." (PMID 40936908, 2025). "However, the association between GSK3β SNPs and MDD was also not replicated in the subgroup of 3231 patients with recurrent depression and 3186 controls among Chinese Han women." (PMID 35126809, 2022). "Although Sema3A, GSK3β, and CRMP2 have been linked to depression, their role in PPD has not been reported." (PMID 36776771, 2022). "Our study suggests the efficacy of NAc DBS in treatment-resistant depression as it significantly increased p-GSK3β levels in the vHipp, and this effect was not confounded by sham electrode implantation." (PMID 34349629, 2021).
depression (continued). "Compared with non-depressed subjects, GSK3β activity was increased in the postmortem ventral PFC from subjects with depression, and GSK3α activity did not change." (PMID 34051074, 2021). "Specifically, GSK3β phosphorylation (which is inhibitory) has been shown to be negatively correlated with depression-like behavior in mice exposed to HFD for 16 weeks, which is consistent with studies showing that the inhibition of GSK3β leads to antidepressant-like effects in mice." (PMID 34276291, 2021). "GSK3β directly phosphorylates FGF14 at S226 and Nav1.6 at T1936, two sites that were found to be disease-related in experimental models of neurodegeneration and of vulnerability to stress and depression, respectively." (PMID 31729429, 2019). "Lithium is a classical, non-competent GSK3β inhibitor and prescribed for the treatment and prophylaxis of bipolar mood disorders and depression." (PMID 28423558, 2017). "Several molecules relevant to pathophysiology of depression, including BDNF, ERK1/2, Akt and GSK3β, could be modulated by agomelatine." (PMID 27877109, 2016). "In the present study, all three doses of GTS (50, 25, and 12.5 mg kg−1 d−1) significantly reversed the downregulated inhibitory phosphorylation of GSK-3β in this depression model, thereby suggesting that GTS may inhibit GSK-3β." (PMID 24523822, 2014). "For instance, GSK-3β inhibitors may be used in conjunction with CREB activators (like rolipram) and BDNF enhancers (like 7,8-DHF) to promote neuroprotection, slow cognitive decline, and lessen depressive symptoms in AD and depression." (PMID 40149774, 2025). "Gsk3b destabilizes the molecular clock by promoting Bmal1 ubiquitination and subsequent degradation, and increased Gsk3b activity has been described in several psychiatric disorders with documented impairment in circadian clock function (e.g. bipolar disorder, schizophrenia, ADHD, and depression)." (PMID 37561236, 2023). "Taken together, these data suggest that the loss of GAD67 from SOM neurons may lead to the development of anxiety-like but not depression-like states mediated by modification of Akt/GSK3β activities." (PMID 31275123, 2019). "A novel non-cholinergic mechanism, the hyper-phosphorylation of GSK-3β, may contribute to its cellular and behavioral (depression) neurotoxicity." (PMID 26824332, 2016). "Consistent with the report that the enzymatic activity of GSK-3β was increased in depressed suicide victims, lower pGSK-3β and pGSK-3β/GSK-3β levels in the hippocampus were found in the SCH rats, which could induce depression-like behavior in this study." (PMID 27252679, 2016). "Our results suggested that the GSK-3β-CREB signaling pathway may contribute to the decreased expression of some plasticity-related proteins in the hippocampus; this pathway may also induce depression-like behaviors." (PMID 26798520, 2015). "Moreover, the mechanism of Glycogen synthase kinase 3β (GSK3β), regulated by signal transducer and activator of transcription 3 (STAT3), may play an important role in the synapse-related pathological mechanisms of depression." (PMID 41428145, 2025). "Finally, we show that in vivo GSK3β inhibition could have beneficial effects on some of the cognitive and depressive-like deficits provoked by chronic unpredictable mild stress (CUMS), which is a widely used model of induced depression." (PMID 36286471, 2022). "Recent post-mortem studies showed increased GSK3β and decreased Akt activities in brains of suicide victims with MDD, but not in suicide victims without depression." (PMID 23449817, 2012). "More important is our present finding about the involvement of PI3K/Akt/FoxO3a, GSK3β, and BDNF, is new and have not been investigated including in animal models of depression." (PMID 34721013, 2021). "Thus, GSK-3β may not be properly inhibited in conditions of decreased 5HT levels in depression." (PMID 31191636, 2019).
glioblastoma (119 papers, 2009 to 2026). The most malignant astrocytic tumor (WHO grade IV). "An earlier study showed that GSK3β suppresses the differentiation of glioblastoma SCs in association with Bmi1, a polycomb group gene required for the self-renewal of neural stem cells." (PMID 32503133, 2020). "In addition, CKIP-1 inhibits the phosphorylation of GSK3β and the underlying mechanism may be associated with suppressing the AKT/GSK3b/b-catenin signaling pathway in human U251 glioblastoma cell line." (PMID 31355268, 2019). "Collectively, these results suggest that GAD1 inhibits the expression of Cyclin D1 and MMP9 via the p-GSK3β/β-catenin pathway, thereby impeding glioblastoma progression." (PMID 41844572, 2026). "One recent study found that GSK3β palmitoylation, mediated by ZDHHC4, decreases p-Ser9 and increases p-Tyr216, leading to continuous activation of GSK3β, promoting tumorigenicity of glioblastoma stem cells." (PMID 40814339, 2025). "This CDK12/GSK3β/PPARD axis was required for glioblastoma cell proliferation and metabolic homeostasis." (PMID 40996961, 2025). "The second PMT-related hub, GSK3β, was found to be less susceptible to STLs: it was reported that only DMAMCL and dihydroartemisinin effectively inhibited the expression and phosphorylation of β-catenin, a downstream effector of GSK3β, in glioblastoma cells." (PMID 39857717, 2025). "ZDHHC4 mediates the palmitoylation and activation of GSK3β, sustaining the stemness of temozolomide-resistant glioblastoma multiforme (GBM) by activating the EZH2-STAT3 signaling axis." (PMID 40814339, 2025). "In a study on glioblastoma, MA unveiled inhibitory effects on GSK-3β and its downstream pathways, splicing factors, PTBP1, SF2/ASF, and hnRNPA1, as well as anti-apoptotic regulators." (PMID 39863145, 2025). "In contrast with our findings, phosphorylation promoted DSB repair, and inhibition of GSK3B induced glioblastoma cell apoptosis." (PMID 41243969, 2025). "We have previously shown that kenpaullone, an adenosine triphosphate (ATP)-competitive GSK3β inhibitor, reversed the temozolomide resistance of glioblastoma patient-derived tumor stem cells." (PMID 38318525, 2024). "Our study identifies GSK3B as a novel glioblastoma cancer gene, and it has been demonstrated to be aberrantly activated in various cancer types, promoting tumor cell proliferation and immortalization." (PMID 38510118, 2024). "Previous studies determined that Chr-A showed inhibitory effects towards human U251 and U87-MG glioblastoma cells in vitro via the Akt/GSK-3β signaling pathway." (PMID 37367654, 2023). "HPCAL1 also activates the Wnt/β‐catenin pathway by enhancing ERK stimulation and inhibiting GSK3β, thereby contributing to the proliferation of glioblastoma." (PMID 35645147, 2023). "Our study has shown that Chr-A has the potential to suppress oncogenesis of glioblastoma by inducing apoptosis through the Akt/GSK-3β signaling pathway." (PMID 37367654, 2023). "In a mouse cell model of glioblastoma (GBM) the c-yes/PI3K-p85 interaction was reported to signal cell invasion via glycogen synthase kinase 3-beta pathway and subsequent expression of matrix metalloproteinases." (PMID 35301281, 2022). "It has been shown that silencing of GSK3β or its inhibition with AR-A01441 reduced the migration of human glioblastoma cell lines: U87, U251, A172, and T98G." (PMID 34440861, 2021). "In human glioblastoma cell line U251, the inhibition of GSK3β with AR-A014418 reduced the expression of membrane-type I-matrix metalloproteinase (MT1-MMP)." (PMID 34440861, 2021). "Similar to the effect on CD8+ memory T-cells, inhibition of GSK3β in mouse glioblastoma-specific CAR-T cells increased their survival, proliferation and memory phenotype generation, as well as enhancing their cytotoxic capacity." (PMID 32503133, 2020). "Previous studies reported that lithium and GSK3-inhibiting indirubins decreased the migration and invasion of glioblastoma cells, suggesting a putative role for GSK3β in tumor invasion." (PMID 32503133, 2020).
glioblastoma (continued). "Paradoxically, a completely deregulated activity of GSK-3β according to modifications in the differential phosphorylation of S9 and Y216 residues was seen in gastrointestinal cancers and glioblastoma compared to "healthy" cells." (PMID 32681294, 2020). "Recently, our group screened compound libraries and identified kenpaullone, a pharmacological GSK3β inhibitor that attenuates the survival of patient-derived glioblastoma SCs via the c-Myc-mediated pathway." (PMID 32503133, 2020). "Pathway analysis on the ingenuity pathway analysis (IPA) platform identified axonal guidance signalling, glioblastoma multiforme signalling, role of Wnt/GSK-3β signalling and ephrin A signalling, among others, as enriched in mGIC." (PMID 31988455, 2020). "Apart from targeting the HIFs, CGs also induces apoptosis in glioblastoma through the activation of GSK3β and by the alteration of microtubule dynamics." (PMID 32784680, 2020). "A growing body of evidence is shedding light on the tumor-promoting roles of GSK3β in diverse cancers, and a recent study has shown that it is involved in glioblastoma cancer stem cell self-renewal." (PMID 31001473, 2019). "In this clinical study, we observed that GSK3β-inhibiting medicines attenuated cell proliferation and invasion of patients’ brain tumors, as well as primary tumors in a mouse glioblastoma model." (PMID 29568361, 2018). "In close relation to the present study, our research group recently reported the results of a clinical trial for treatment of recurrent glioblastoma patients with repurposed GSK3β-inhibiting medicines in combination with temozolomide." (PMID 29568361, 2018). "Deregulated GSK-3β expression promotes gastrointestinal, pancreatic, and liver cancers and glioblastomas." (PMID 28427240, 2017). "GSK3β was shown to be upregulated in glioblastoma cells, and assist in stem cell maintenance by phosphorylating and stabilizing KDM1A." (PMID 29053791, 2017). "GSK3β has been previously demonstrated to be a direct target in glioblastoma multiforme and podocyte." (PMID 28484287, 2017). "Therapeutic effects of GSK-3β inhibition have been shown in epithelial as well as in hematopoietic, neuronal and musculoskeletal cell malignancies including leukemia, glioblastoma and rhabdomyosarcoma." (PMID 27780915, 2016). "Blocking GSK-3β phosphorylation at Ser9 has been reported to attenuate cell proliferation while concomitantly stimulating caspase-3 mediated apoptosis in glioblastoma stem-like cells." (PMID 26902162, 2016). "Collectively, these results indicated that GSK3β was a direct target of miR-101 in glioblastoma cells." (PMID 27792996, 2016). "In contrast, inhibition of GSK3β compromises the survival, proliferation and invasion of glioblastoma cells." (PMID 27846906, 2016). "Glioblastoma is one of the most aggressive forms of primary brain tumors of glial cells, including aberrant regulation of glycogen synthase kinase 3β (GSK3β) and splicing factors deregulation." (PMID 24550987, 2014). "Similar findings of GSK-3β inhibition were described for glioblastoma, in which a reduction of stem cell markers was described upon GSK-3β inhibition subsequently leading to impaired neurosphere formation and lessened clonogenicity." (PMID 25344861, 2014). "We previously demonstrated that deregulated expression, activity and phosphorylation of GSK3β are distinct features of gastrointestinal cancers and glioblastoma and that GSK3β sustains the survival and proliferation of these tumor cells." (PMID 23408967, 2013). "GSK3β also plays an important role in regulating differentiation and growth arrest in malignant glioma cells and glioblastoma." (PMID 22046442, 2011). "Few studies had focused on the role of GSK3β in the cellular response to chemotherapy until we reported that GSK3β inhibition sensitizes glioblastoma cells to chemotherapeutic agents (e.g., temozolomide, ACNU) and ionizing radiation." (PMID 24212624, 2011).